NSUN3 (NOP2/Sun RNA methyltransferase 3)
Description:
Mitochondrial tRNA methyltransferase that mediates methylation of cytosine to 5-methylcytosine (m5C) at position 34 of mt-tRNA(Met). mt-tRNA(Met) methylation at cytosine(34) takes place at the wobble position of the anticodon and initiates the formation of 5-formylcytosine (f(5)c) at this position. mt-tRNA(Met) containing the f(5)c modification at the wobble position enables recognition of the AUA codon in addition to the AUG codon, expanding codon recognition in mitochondrial translation.
Synonyms: MSTP077; FLJ22609; COXPD48; MST077
Tractability: PROTAC: ubiquitination databases record sites on it.
Target class: Enzyme; Transferase
Gene: Protein-coding gene on chromosome 3 (94,062,980 to 94,131,832, forward strand). Ensembl gene ENSG00000178694.
Subcellular location: Mitochondrion matrix
Gene Ontology:
Molecular function: protein binding; tRNA (cytidine-5-)-methyltransferase activity; methyltransferase activity; RNA methyltransferase activity; S-adenosylmethionine-dependent methyltransferase activity
Biological process: regulation of mitochondrial translation; tRNA wobble base cytosine methylation; rRNA methylation; RNA processing
Cellular component: mitochondrial matrix; mitochondrion
Genetic constraint (gnomAD): Loss-of-function variants: 16 observed, 30.57 expected, observed/expected ratio (o/e) 0.52, 90% interval 0.35 to 0.8. The upper end of that interval is the gene's LOEUF score, 0.8, which puts it in group 3 of 6, group 1 being the genes least tolerant of losing a copy. Missense variants: 329 observed, 353.8 expected, observed/expected ratio (o/e) 0.93, 90% interval 0.85 to 1.02. Synonymous variants: 134 observed, 135.55 expected, observed/expected ratio (o/e) 0.99, 90% interval 0.86 to 1.14.
Homologues: Orthologues: chimpanzee NSUN3 (99% identical), macaque NSUN3 (98% identical), pig NSUN3 (90% identical), rabbit NSUN3 (90% identical), dog NSUN3 (87% identical), guinea pig NSUN3 (84% identical), mouse Nsun3 (82% identical), rat Nsun3 (72% identical), tropical clawed frog nsun3 (61% identical), zebrafish nsun3 (50% identical). Paralogues in human: NSUN4 (34% identical), NSUN2 (24% identical).
Diseases named in the same sentence as NSUN3 in open-access papers:
NSUN3 is named in the same sentence as 50 diseases in open-access papers, as found by Europe PMC text mining. Sharing a sentence is not in itself a finding about the gene and the disease. The quoted sentences say what the papers report.
head and neck squamous cell carcinoma (4 papers, 2022 to 2025). A squamous cell carcinoma that arises from any of the following anatomic sites: lip and oral cavity, nasal cavity, paranasal sinuses, pharynx, larynx, and salivary glands. "For instance, knocking down NSUN3 increases the infiltration of M1 macrophages while reducing M2 macrophages, thereby promoting the progression of head and neck squamous cell carcinoma." (PMID 41256854, 2025). "Current studies have revealed that NSUN3 expression is upregulated in patients with low-grade glioma and head and neck squamous cell carcinoma (HNSCC), and NSUN3-mediated m5C modification of tRNA enhances metastasis by stimulating the translation of mitochondrial mRNA." (PMID 37325635, 2023).
leukaemia (4 papers, 2018 to 2024). "In a recent report, NSUN3 was found to form a complex with hnRNPK, DNMT2 and P‐TEFb at elongating RNA polymerase II sites in leukemia cells implying a role for NSUN3 in transcriptional regulation in the nucleus." (PMID 30311405, 2019). "In contrast, the interactions between hnRNPK and DNMT2 as well as NSUN3 were insensitive to 5-AZA in the same leukaemia cells." (PMID 29563491, 2018). "Our data demonstrate that hnRNPK directly interacts with a subset of RCMTs, namely DNMT2 and NSUN3, to form a functional complex important for the integrity of these proteins and survival of leukaemia cells." (PMID 29563491, 2018). "In contrast, the markedly increased interactions between RNA-pol-II CTD-S2P and NSUN3 as well as DNMT2 in these 5-AZA-resistant M2AR leukaemia cells were highly sensitive to 5-AZA." (PMID 29563491, 2018). "Additionally, studies in leukemia have shown that NSUN3 and DNMT2 can regulate the chromatin structures by directly binding hnRNPK and further modulating 5-Azacitidine response." (PMID 37666951, 2023). "Knockdown experiments with the siRNAs targeting various RCMTs demonstrated that downregulation of hnRNPK, NSUN3 and DNMT2 preferentially inhibited the growth of the 5-AZA-sensitive SC leukaemia cells (top)." (PMID 29563491, 2018). "RNase digestion-coupled immunoprecipitation (IP) and co-immunoprecipitation (co-IP) demonstrated RNA-independent, direct binding of hnRNPK to a subset of RCTMs, namely, DNMT2 and NSUN3, in OCI-M2 leukaemia cells." (PMID 29563491, 2018). "In contrast, siRNA knockdown of NSUN1 or NSUN2 significantly reduced both the NSUN1 and NSUN2 proteins, but had little effects on the hnRNPK/NSUN3/DNTM2 complex and total RNA-pol-II in the leukaemia cells." (PMID 29563491, 2018).
lung squamous cell carcinoma (3 papers, 2023 to 2025). "NSUN3 and NSUN4 have also been found to be related to immune cells in lung squamous cell carcinoma (LUSC); notably, NSUN3 was closely associated with CD8+ T cell infiltration, and NSUN4 was closely associated with neutrophils." (PMID 37485079, 2023). "Related studies have also confirmed that NSUN3 and NSUN4 can predict the prognosis of lung squamous cell carcinoma and regulate the immune microenvironment." (PMID 40370440, 2025). "In lung squamous cell carcinoma (LUSC), the m5C regulatory factors NSUN3 and NSUN4 are highly expressed compared to normal lung tissue and are associated with poor prognosis." (PMID 40370440, 2025).
mitochondrial encephalomyopathy (3 papers, 2020 to 2022). A heterogenous group of disorders characterized by alterations of mitochondrial metabolism that result in muscle and nervous system dysfunction. "Deletion of functional mutations in NSUN3 is associated with multisystem mitochondrial diseases such as early-onset mitochondrial encephalomyopathy and epilepsy." (PMID 36035311, 2022). "The novel compound heterozygous NSUN3 missense variants c.421G>C (p.A141P) and c.454T>A (p.C152S) were detected in one patient with early-onset mitochondrial encephalomyopathy and seizures (II:3)." (PMID 32488845, 2020). "Here, we report novel biallelic NSUN3 missense variants in a South Asian patient with early-onset mitochondrial encephalomyopathy and seizures." (PMID 32488845, 2020). "We report a South Asian patient with early-onset mitochondrial encephalomyopathy and seizures harbouring novel, compound heterozygous NSUN3 missense variants c.421G>C (p.A141P) and c.454T>A (p.C152S)." (PMID 32488845, 2020). "In conclusion, we report novel biallelic NSUN3 missense variants causing early-onset mitochondrial encephalomyopathy and seizures, thereby expanding the molecular and phenotypic spectrum of NSUN3-related mitochondrial disease." (PMID 32488845, 2020). "Here, we report a patient with early-onset mitochondrial encephalomyopathy and seizures in whom the novel biallelic NSUN3 missense variants c.421G>C (p.A141P) and c.454T>A (p.C152S) were detected." (PMID 32488845, 2020).
oral cancer (3 papers, 2022 to 2024). "In human oral cancer, higher NSUN3 expression correlated with more advanced pathological states, and NSUN3 activity was particularly elevated near the tumor–stroma border, the site of invasion initiation." (PMID 38476632, 2024). "Recently, researchers have reported that NSUN3 is participating in the mitochondrial tRNA modifications and shaped metabolic plasticity in metastasis of oral cancer." (PMID 36169095, 2022).
lung carcinoma (2 papers, 2024 to 2025). "LEPR gene polymorphisms are linked to lung function decline in COPD, and NSUN3 is associated with lung cancer development in COPD." (PMID 39143598, 2024). "The impact of NSUN3 expression modulation on lung cancer cell viability and proliferation was assessed through CCK-8 assays and colony formation experiments." (PMID 40279954, 2025). "Recently, a seven-gene m6A/m5C risk model, comprising METTL3, NPLOC4, RBM15, YTHDF1, IGF2BP1, NSUN3, and NSUN7, was developed to stratify the prognosis of early-stage lung cancer." (PMID 40279954, 2025).
lymph node metastases (2 papers, 2022 to 2026). "Elevated NSUN3 expression, along with advanced pTNM stage and lymph node metastasis, constituted independent risk factors for poor overall survival." (PMID 42100395, 2026). "The expression of genes that correlate with high levels of NSUN3—and therefore high levels of m5C—predicted lymph node metastases and poor patient prognosis." (PMID 35768510, 2022). "Both the pathological stage of these cancers and the presence of lymph node metastasis at the time of diagnosis progressively increased with NSUN3 levels." (PMID 35768510, 2022). "In summary, the NSUN3-driven gene signature is prognostic for lymph node metastasis and for higher pathological stage in patients with HNSCC." (PMID 35768510, 2022). "To confirm our observation in tumoroids that metastasis-initiating cells needed high mitochondrial activity for invasion, we labelled primary tumour sections from patients with lymph node metastasis for NSUN3." (PMID 35768510, 2022).
optic atrophy (2 papers, 2024 to 2025). A disorder characterized by loss of optic nerve fibers. "In this study, we described a patient with non-syndromic optic atrophy in the presence of an autosomal recessive disease-associated variant in the NSUN3 gene." (PMID 38790159, 2024). "Pathogenic or likely pathogenic biallelic variants in NSUN3 disrupt mt-tRNAMet methylation and mitochondrial translation leading to mitochondrial disease ranging from mild isolated optic atrophy to a severe multisystemic phenotype with possible limited life expectancy." (PMID 40465263, 2025). "Currently, two probands are described in the literature with NSUN3 variants and mitochondrial disease, but optic atrophy has not been described in these cases." (PMID 38790159, 2024). "If ES or GS is not available and even if it may be a rare cause, the NSUN3 gene should be added to diagnostic optic atrophy and mitochondrial disease gene panels when investigating patients who are suspected to have an isolated or syndromic inherited optic neuropathy." (PMID 40465263, 2025).
Optic neuropathy (2 papers, 2024 to 2025). "In conclusion, pathogenic variants in NSUN3 can cause optic neuropathy." (PMID 38790159, 2024).
oral squamous cell carcinoma (2 papers, 2022 to 2026). "To inhibit the formation of both tRNAMet modifications, we depleted the methyltransferase NSUN3 in four oral squamous cell carcinoma (OSCC) cell lines using two different short hairpin RNAs (shRNAs)." (PMID 35768510, 2022).
Sepsis (2 papers, 2023 to 2025). Sepsis is defined as life-threatening organ dysfunction caused by a dysregulated host response to infection. "Eventually, NSUN3 enhanced sepsis-associated acute kidney injury by stabilizing TIFA mRNA through m5C." (PMID 41462962, 2025). "Knocking down NSUN3 alleviated LPS induced HK-2 cell damage and sepsis-associated acute kidney injury in mice by reducing TIFA expression." (PMID 41462962, 2025). "In the mechanism of sepsis-associated acute kidney injury, NSUN3 increased the stability of TIFA mRNA and upregulated its expression through m5C modification." (PMID 41462962, 2025). "NSUN3-mediated m5C modification enhanced TAK1 mRNA stability in HULEC-5a cells during sepsis-induced pulmonary injury." (PMID 41462962, 2025). "NSUN3 and TIFA expressions were upregulated in mice with sepsis-associated acute kidney injury and lipopolysaccharide (LPS)-induced HK-2 cells." (PMID 41462962, 2025). "Lastly, NSUN3-mediated m5C modification promoted sepsis-induced pulmonary injury by regulating inflammation." (PMID 41462962, 2025). "NSUN3-mediated TAK1 m5C modification promoted sepsis-induced pulmonary injury by regulating inflammation." (PMID 41462962, 2025). "In addition, NSUN3 and m5C RNA methylation modification has been established to regulate metabolism in metastasis, which is in consistent with our findings in sepsis." (PMID 37701433, 2023). "In cluster 2, the physiological function analysis demonstrated that NSUN3 may be involved in amino acid metabolism in sepsis." (PMID 37701433, 2023).
breast carcinoma (1 paper, 2019). "SK2 KD universally downregulated expression of CAPZA1 (inhibition of autophagy and EMT) and also decreased expression of NSUN3, ADPGK and KLHDC10 in prostate and ITGAV in breast cancer cell lines." (PMID 30971929, 2019).
cervical cancer (1 paper, 2022). A primary or metastatic malignant neoplasm involving the cervix. "Although NSUN2 is the main methyltransferase for m5C methylation on mRNA, we extended to explore the expression of all potential m5C methyltransferases (NOP2, NSUN3, 4, 5, 6, 7, and DNMT2) in cervical cancer, ovarian cancer, and endometrial cancer." (PMID 35280737, 2022).
cutaneous melanoma (1 paper, 2022). A primary melanoma arising from atypical melanocytes in the skin. "Several m5C-regulators are associated with overall survival prognosis in cutaneous melanoma (DNMT2, NSUN1, NSUN3, NSUN6 and YBX1)." (PMID 36060802, 2022).
developmental delay (1 paper, 2020). "Patients with variants in MTFMT and NSUN3 have been described with microcephaly, developmental delay muscular weakness, and CPEO." (PMID 33426505, 2020).
esophagus cancer (1 paper, 2020). "Notably, the mutation frequencies of NSUN2 in esophagus and stomach cancers, NSUN3 in esophagus cancer, and ALYREF in liver cancer were particularly high." (PMID 33365328, 2020).
gout (1 paper, 2022). A condition characterized by painful swelling of the joints, which is caused by deposition of urate crystals. "The consistent expressions of NSUN3 at the RNA and protein level in HEK293 cell lines suggest the importance of 5-methylcytosine (m5C) in hyperuricemia and gout." (PMID 36148448, 2022).
Hypertension (1 paper, 2023). The presence of chronic increased pressure in the systemic arterial system. "Another reason for choosing heart is that a hypertension patient having a mt-tRNAMet mutation that can reduce NSUN3-mediated modification of mt-tRNAMet, showed left ventricle posterior wall thickening during his 60s and 70s26,30." (PMID 36949224, 2023).
low grade glioma (1 paper, 2023). A grade I or grade II glioma arising from the central nervous system. "NSUN3 has been considered to be M5 C regulators in low-grade glioma." (PMID 37934565, 2023).
lung adenocarcinoma (1 paper, 2010). A carcinoma that arises from the lung and is characterized by the presence of malignant glandular epithelial cells. "We performed high-resolution array comparative genomic hybridization analysis of lung adenocarcinoma in sixty never smokers and identified fourteen new minimal common regions (MCR) of gain or loss, of which five contained a single gene (MOCS2, NSUN3, KHDRBS2, SNTG1 and ST18)." (PMID 21151896, 2010).
malaria (1 paper, 2025). Malaria is a serious and sometimes fatal disease caused by a parasite that commonly infects a certain type of mosquito which feeds on humans. "To trace the evolutionary relationship of NSUN3 proteins in eukaryotes, including malaria parasite species, we constructed a phylogenetic tree using the whole sequences of NSUN protein ortholog." (PMID 40148982, 2025).
Obesity (1 paper, 2025). Accumulation of substantial excess body fat. "Given that mitochondrial dysfunction is known to be a consequence of obesity, depot-specific NSUN3 gene expression may indicate at mitochondrial m5C potentially involved in obesity in a depot-specific manner." (PMID 41030849, 2025).
prostate carcinoma (1 paper, 2025). A carcinoma that arises from epithelial cells of the prostate gland. "NSUN3 and NSUN4 have received less attention in prostate cancer research, but they may play a role in chemotherapy resistance and tumor advancement, potentially serving as risk factors for prostate cancer." (PMID 40809690, 2025).
tumor (24 papers, 2020 to 2026). "RNA 5-methylcytosine (m5C) modification, mediated by methyltransferases such as NSUN3, is implicated in tumor progression; however, the specific function of NSUN3 in OSCC remains largely unexplored." (PMID 42100395, 2026). "As cancer cells readily use glycolysis for energy production, even when oxygen is available (the Warburg effect), it was unsurprising that primary tumour growth was unaffected by the loss of NSUN3." (PMID 35768510, 2022). "The authors further investigated the mechanism by which NSUN3 promotes tumor immune evasion and found that NSUN3 enhances the stability of PD-L1 through tumor endogenous mechanisms, primarily via m5C modification." (PMID 40279954, 2025). "In this study, for the first time, the regulatory role of NSUN3 in the body's anti-tumor immune effect was discovered and its mechanism was initially discussed." (PMID 40279954, 2025). "Previously, NSUN3 was found to be involved in the modification of tumor mitochondrial m5C to regulate tumor cell metastasis, but as an independent enzyme, it exclusively promotes mitochondrial m5C formation." (PMID 39019857, 2024). "Mechanistically, NSUN3 promotes tumor progression by regulating immune infiltration, and ALYREF enhances mitochondrial activity and intracellular energy metabolism, which ensures continuous energy supplies for timorous tissues." (PMID 37325635, 2023). "NSUN3, a putative tRNA methyltransferase, plays a role in tumor progression, immune cell infiltration and multisystem mitochondrial diseases." (PMID 37325635, 2023). "Consistent with our observation that inhibition of methylation enhanced glycolysis in vitro, NSUN3-depleted tumours also exhibited an increase in glycolysis and upregulation of glucose transporter 1 (GLUT1) in vivo." (PMID 35768510, 2022). "In conclusion, inhibition of mitochondrial translation fully recapitulated the loss of a functional NSUN3 protein by preventing cell invasion and reducing the number of CD36-dependent metastasis-initiating tumour cells in vitro and in vivo." (PMID 35768510, 2022). "Together, our data indicate that the activity of NSUN3 is higher close to the tumour–stroma border, where the activation of invasion occurs." (PMID 35768510, 2022). "Expression of NSUN3 protein was highest in primary tumours from patients with regional lymph node metastases at the time of diagnosis, and was associated with higher pathological staging of the primary tumours." (PMID 35768510, 2022). "Principal component analyses using all transcribed mitochondrial genes (n = 1158; MitoCarta2.0) clearly separated the tumours according to NSUN3 expression, an effect that was highly reproducible and independent of the shRNA." (PMID 35768510, 2022). "The in vivo tumorigenic role of NSUN3 was investigated using subcutaneous tumor xenograft models." (PMID 40279954, 2025). "NSUN3 is a tumor driver in NSCLC pathogenesis that functions stably through PDL1 mRNA." (PMID 41462962, 2025). "Furthermore, NSUN3 deficiency enhanced CD8+ T cell cytotoxicity towards NSCLC cells and inhibited tumor growth in vivo." (PMID 41462962, 2025). "We note that similar to many other tRNA modification enzymes that are important for body development, NSUN3 also supports the progression of cancer; NSUN3-mediated mitochondrial translation is required for metastasis-initiating tumor cells to activate invasion and dissemination." (PMID 39719325, 2025). "In human oral cancer cells, NSUN3‐mediated m5C deficiency of mt‐tRNA does not influence primary tumour growth but impedes metastasis due to impaired mitochondrial metabolism." (PMID 38943267, 2024). "Accordingly, NSUN3-depleted primary tumours were histologically highly similar to controls." (PMID 35768510, 2022). "NSUN3 protein levels were highest at the invasive front of the tumours." (PMID 35768510, 2022).